IL6 (interleukin 6)
Diseases named in the same sentence as IL6 in open-access papers (continued):
Sharing a sentence is not in itself a finding about the gene and the disease.
cancer (continued). "PL EO can exert its anti-inflammatory effects by several mechanisms, Firstly, anti-inflammatory activities can reduce cancer by the attenuating the pro-inflammatory cytokines production, such as TNF-α and IL-6, which have been shown to promote cancer growth and progression." (PMID 38635559, 2024). "The role of IL-6 in cancer immunotherapy remains a topic of ongoing debate." (PMID 39766045, 2024). "It is widely accepted that effusions may provide a premetastatic niche supplying cancer tissue with various growth factors, including Il-6, IL-8, and IL-β1." (PMID 38891100, 2024). "IL-6 constitutes a significant factor in a range of physiological processes, encompassing cell proliferation, migration, invasion, apoptosis, angiogenesis, and the growth and differentiation of cancer cells." (PMID 38673838, 2024). "Similarly, in human intrahepatic cholangiocarcinoma, a study identified CD146-positive CAFs as vCAFs exhibiting high expression of microvasculature signatures and IL6, and promoting cancer cell malignancy." (PMID 38453816, 2024). "Previous data by others have shown that IL6 and other cytokines regulate glycolysis in cancer." (PMID 38650935, 2024). "Interleukin-6 (IL-6) is known to promote cancer progression and treatment resistance." (PMID 38338683, 2024). "Some oral bacteria, such as Streptococcus and Fusobacterium, may reduce levels of short-chain fatty acids (SCFAs) and elevate tumor necrosis factor-alpha (TNF-α) and interleukin-6 (IL-6), potentially promoting cancer cell proliferation." (PMID 39456670, 2024). "In addition, IL-6, which is a critical inflammation mediator of cancer cachexia driving the expression level of UCP1, is upregulated." (PMID 39519503, 2024). "Therefore, the positive effects of IL-6 on T cells can be considered while developing anti-IL-6 agents for cancer therapy." (PMID 38303018, 2024). "IL-6 trans-signaling plays a key role in cancer progression." (PMID 39103836, 2024). "Myokines, such as osteopontin and irisin, are associated with cancer development and progression in humans, and preclinical models implicate myokines, such as oncostatin M and interleukin‐6 (IL‐6), in cancer cell growth, migration, invasion, apoptosis and angiogenesis." (PMID 38887915, 2024). "In human cancer and primary cells, sgp130Fc inhibited IL6, IL11, OSM and CT1 cis-signalling." (PMID 38338642, 2024). "We hypothesized that IL-6 would be a more sensitive marker than CRP in the prognostication of cancer cachexia." (PMID 38539528, 2024). "The active compound 6-chloro-N-(4-nitrobenzyl) benzo[d] thiazol-2-amine (compound B7) was screened through a series of bioactivity assessments, which significantly inhibited the proliferation of A431, A549 and H1299 cancer cells, decreased the activity of IL-6 and TNF-α, and hindered cell migration." (PMID 38562527, 2024). "TNF-α, IL-6, and IL-11 play a critical role in promoting the development and progression of cSCC by creating an inflammatory environment that supports the growth and survival of cancer." (PMID 40013270, 2024). "Furthermore, this pattern was associated with the secretion of IL-6 and TGF-β1 by cancer cells, with IL-6 inducing Th17 cells and TGF-β1 inducing Tregs, and the IL-6/Th17 axis was associated with EMT features." (PMID 39683528, 2024). "Excess body fatness is linked to elevated levels of hormones and substances from fat cells that promote inflammation, such as leptin, TNF-α, and IL-6, which could potentially stimulate the growth of cancer cells." (PMID 39317703, 2024). "The substantial overlap in metabolically regulated genes—such as IL6, IL1B, and COL1A1—in lung epithelial cells associated with PH and all published cancer analyses (where metabolites were elevated) suggests shared mechanisms linking transcriptional changes to genomic alterations." (PMID 39635438, 2024).
cancer (continued). "In the present study, although the extent of senescence elicited by DNA‐damaging agents and CDK4/6i was similar, CDK4/6i‐induced senescent cancer cells showed significantly lower expression of well‐known pro‐inflammatory SASP such as IL‐6, CXCL1, CXCL8, and TGF‐β." (PMID 37854019, 2024). "Consequently, elevated IL-6 levels can signal cytokine-based pathway activation in acute inflammatory conditions (e.g., sepsis) or chronic diseases (e.g., cancer and/or heart conditions)." (PMID 39412695, 2024). "However, the applicability of IL-6 inhibition to other diseases, including cancer, was also investigated." (PMID 38715108, 2024). "The unexpected effects of the D + Q combination on the IL-6 levels found in our study may be an obstacle to its use as adjuvant therapy in cancer treatment." (PMID 38612842, 2024). "Also, metabolic remodeling and resistance to apoptosis are cancer hallmarks to which IL-6 activity is attributed." (PMID 39201656, 2024). "Interleukin-6 (IL-6): IL-6 is a pro-inflammatory cytokine that plays a dual role in cancer." (PMID 38397971, 2024). "IL-6 increases Huh-7 cell migration and enhances cancer stemness." (PMID 38333871, 2024). "Furthermore, treatment with CI or celecoxib reduced IL-6 level, one of the clinical indicators of cancer cachexia, in the serum compared to the CT26 group." (PMID 39624846, 2024). "Moreover, IL-6 significantly enhanced cell proliferation and cancer stemness, while such effects were exacerbated by SPOP knockdown in 5637 cells." (PMID 39479456, 2024). "Of note, this chronic phlogistic state has been also observed in clinical practice and reported in the literature, with the help of serum inflammatory markers such as C-reactive protein (CRP) and proinflammatory cytokines such as interleukin 6 (IL-6) in both cancer and HF." (PMID 38397436, 2024). "However, there seems to exist a possibility of interplay of COVID-19 and cancer in IL-6/JAK/STAT signaling." (PMID 39770330, 2024). "IL-6, a pro-inflammatory cytokine, has a broad impact on tumorigenesis, growth and progression, with its signaling pathway playing a key role in the invasion and metastatic formation of cancer cells." (PMID 39697224, 2024). "In cancer and infectious diseases, however, the situation is more complicated as IL-6 might still be of importance for the immune-mediated disease control." (PMID 39518029, 2024). "NFκB signaling induces inflammation in cancer and targets IL-6 downstream." (PMID 39337548, 2024). "Studies on the role of EVs in angiogenesis have demonstrated that cancer cell-derived EVs contain interleukin-6 (IL-6) and vascular endothelial growth factor (VEGF), potent pro-angiogenic factors that enhance endothelial cell invasion and organization in tubule-like structures." (PMID 38765006, 2024). "The presence of these cells leads to the continuous production of pro-inflammatory mediators, including the release of cytokines such as TNF-α, interleukin-1 (IL-1) and interleukin-6 (IL-6), and chemokines, which promote cancer cell survival, proliferation, angiogenesis, and invasion." (PMID 39766152, 2024). "Most importantly, the concentration of CCL2 and IL-6, which were secreted only by the MSCs, were doubled in the co-cultures suggesting that cancer cells can induce the secretion of some factors, like pro-inflammatory cytokines which could support their growth." (PMID 38674102, 2024). "Additionally, the inflammatory signals produced by SASP, including IL-6, have been shown to influence cancer stem cells (CSCs) by activating pathways like STAT3 and NF-κB, which are crucial for maintaining the stemness and self-renewal capabilities of CSCs." (PMID 39335106, 2024). "Some studies reported IL-6 production by cancer cells, i.e., CC cells." (PMID 38541074, 2024). "Targeting IL-6 shows promise as a therapeutic approach for transplantation and cancer treatment." (PMID 38564670, 2024).
cancer (continued). "Similarly, the researchers examined the effect of GNP on IL-6 protein secretion in the same MCF-7 cancer cells treated with GNP and PMA." (PMID 38338683, 2024). "Our results from multiple cancer models suggest that targeting IL-6 signaling in the brain, or more specifically in the AP, could be an effective avenue for treating cancer cachexia." (PMID 38824130, 2024). "Neutralization of IL-6 or β3-AR has a substantial positive impact on alleviating cancer cachexia." (PMID 38334644, 2024). "This particular distribution may have contributed to the lower levels of IL6 and TNFα in the plasma of the cancer group." (PMID 38339282, 2024). "Secondly, although the study examined the effects of tRF-GluCTC on IL-6 expression, the roles of other cancer-related cytokines remain unknown." (PMID 38291031, 2024). "In breast tissues, LPS binds to Toll‐like receptor 4 and activates the nuclear factor kappa B signaling pathway, promoting the release of inflammatory cytokines such as tumor necrosis factor‐α and interleukin (IL)‐6, thereby promoting cancer cell proliferation and survival." (PMID 38485288, 2024). "IL-6 has also been suggested to be a cachectic factor in cancer patients." (PMID 38956273, 2024). "We suggest that the efficiency of the calycosin‐based strategy may be improved by combining it with anti‐IL‐6 therapy for cancer treatment." (PMID 37974543, 2024). "IL-6 is a pleiotropic cytokine present in both immune responses (by stimulating B lymphocytes) and nonimmune processes such as acute or chronic inflammation, autoimmune disorders, and even cancer." (PMID 38257150, 2024). "Some cancers, especially hematologic cancers, may release cytokines like IL-1, IL-6, and TNF-α, that negatively impact megakaryocytes and suppress platelet production, explaining some cases of cancer-associated thrombocytopenia." (PMID 39114075, 2024). "However, its LOD is higher than that of the labeled immunosensor, impacting its practical applicability in the detection of overexpressed IL6 in diseases such as cancer." (PMID 39432122, 2024). "Therefore, the regulatory pathway of SLC7A11 by the ERO1α/IL-6/STAT3 axis presents in human cancer cells with hyperactivated mTORC1 signaling." (PMID 38610018, 2024). "IL-6 is a cytokine that can stimulate cancer cell proliferation and angiogenesis." (PMID 39336742, 2024). "Indeed, unlike apoptosis, pyroptosis aims at facilitating inflammation by the release of proinflammatory intracellular contents, including IL-1 and IL-6, in response to various pathological stimuli, mainly microbes but also cancer." (PMID 38673758, 2024). "Cancer cell motility was increased by cytokines such as IL-6, IL-8 and VEGF." (PMID 39120301, 2024). "Inhibition of IL-6 signaling pathways or neutralization of IL-6 itself has shown promise in preclinical and clinical studies, emphasizing the importance of targeting IL-6 for effective cancer therapy." (PMID 38338683, 2024). "It was also shown that IL-6 was abnormally hyperactivated in different cancers." (PMID 39770330, 2024). "Inhibiting the release of Apelin peptide by cancer cells leads to an increase in pro-inflammatory responses in co-cultured macrophages, resulting in a significant upregulation of genes like IL-1β, IL-6, and TNF-α, along with a marked reduction in anti-inflammatory cytokine levels." (PMID 38650924, 2024). "In addition, the monoclonal anti-IL-6R antibody tocilizumab increases apoptosis in cancer cells through the IL-6/Jak1/STAT3 axis, promoting tumorigenesis, invasion and antiapoptotic proteins expression in gastric cancer." (PMID 39075612, 2024). "This means that with an increased IL-6 serum level of ˃28.7 pg/mL, the risk of being diagnosed with advanced-stage (III–IV stage) cancer increased significantly, i.e., 2.9-fold higher compared to early-stage cancer." (PMID 38541074, 2024). "IL-6 induces polarization of M2-macrophages, which in turn promotes cancer metastasis." (PMID 38482486, 2024).
cancer (continued). "Similarly, adipocytes in the TME are influenced by cancer cells to produce elevated levels of IL-6, which enhances malignancy by promoting invasiveness and other hallmarks of cancer." (PMID 39518143, 2024). "However, it presents a LOD and linear range comparable with other reports and within the ranges of clinical interest for detecting overexpressed IL6 typical of diseases such as cancer." (PMID 39432122, 2024). "Interestingly, although IL-6 and NFκB are elevated in cancer cachexia, rodent models and human studies have shown improved cancer cachexia and survival with exercise, but with unexpected key mechanistic results, such as increased IL-6 and NFκB signaling." (PMID 38254849, 2024). "Additionally, IL-6 promotes repair processes and inhibits cell death signals, protecting cancer cells from oxidative stress, apoptosis, and DNA damage brought on by therapy." (PMID 38803729, 2024). "Also, IL-6, IL-17, and TNFα were found at higher levels, which suggest that cytokines act in parallel to modulate immune responses in cancer." (PMID 38279220, 2024). "IL6 can be produced by various cell populations of the cancer microenvironment." (PMID 38540309, 2024). "Given its central role in cancer biology, targeting the IL-6/GP130 pathway has emerged as a promising therapeutic strategy for cancer treatment, with ongoing research focusing on developing novel inhibitors to effectively disrupt aberrant signaling and improve patient outcomes." (PMID 39451730, 2024). "In addition to IL-6-related immunosuppression and poor prognosis in most types of cancers, this cytokine has often been found to be involved in resistance to treatment including all non-surgical modalities: chemo-, radio-, and immunotherapy." (PMID 39518029, 2024). "Notably, CAFs are recognized crucial IL-6 sources in cancers, with numerous studies emphasizing IL-6's role in cancer cell-CAF interaction." (PMID 38311608, 2024). "Our findings emphasize that the circNOX4/FAP/IL-6 axis could be exploited as a therapeutic target for CAF-based cancer therapy." (PMID 38459511, 2024). "Also, IL6 positively correlates with TRPA1 in many cancers but negatively in kidney renal papillary cell carcinoma (KIRP)." (PMID 39770499, 2024). "The classic and trans-signaling pathways of IL-6 provide insights into the intricate mechanisms by which IL-6 may contribute to cancer progression." (PMID 38689325, 2024). "Combining antagonists of the IL-6 pathway with other treatment approaches holds promise for enhancing efficacy and improving patient outcomes, and ongoing clinical trials are evaluating the safety and efficacy of IL-6 inhibition in cancer patients." (PMID 38689325, 2024). "Integrating biomarker analysis, such as inflammatory markers like IL-6, may uncover the mechanisms linking TC and cancer outcomes." (PMID 39767804, 2024). "A high production of IL-6 by PBMCs from cancer patients was reported previously." (PMID 39518029, 2024). "IL6-JAK/STAT pathway upregulates CSC-associated NANOG and Octamer-Binding Transcription Factor-4 (OCT4) gene expression, enhancing stemness and malignancy of cancer cells." (PMID 39766086, 2024). "Interestingly, as demonstrated in this study, sera from cancer patients were found to stimulate IL-6 production by PBMCs from healthy donors, creating a basis for further analyses of such serum factors." (PMID 39518029, 2024). "It is now understood that IL-6 is secreted by cancer cells, inflammatory cells, and stromal cells." (PMID 39251966, 2024). "DRs for IL-6 are being researched as potential treatment options for diseases involving inflammation, like rheumatoid arthritis, inflammatory bowel disease, and certain cancers." (PMID 39184952, 2024). "In addition, higher TG2 expression levels have been shown to induce IL6 secretion and cancer cell aggressiveness." (PMID 38650935, 2024).
cancer (continued). "Besides, circulating inflammatory cytokines, e.g., TNF-α, IL-6, and IL-10 are discussed as potential prognostic oncomarkers in BC patients due to their contribution to cancer proliferation and invasion." (PMID 38464730, 2024). "Thus, cancer progression and systemic IL-6 application lead to increased activities in a common AP network." (PMID 38824130, 2024). "In addition, IL-6 activates STAT3 and is associated with advanced-stage disease and reduced survival in cancer." (PMID 38539448, 2024). "Macrophages M1, on the other hand, produced interleukin-6 (IL-6), interleukin-23 (IL-23), reactive oxygen species (ROS), and other inflammatory mediators to enhance the inflammatory response, which impeded the growth of cancer." (PMID 39239548, 2024). "In vitro, STAT3 activation and IL-6 mRNA levels varied greatly among different cancer cell lines." (PMID 38274367, 2024). "IL-6 is a cytokine that has numerous and diverse biological functions, and it is well-known for its pleiotropic effects (i.e. the immune system, skeletal muscle, and nervous system, hematopoietic system, liver function and cancer)." (PMID 39301315, 2024). "Notably, neutralizing IL-6 in the brain or suppressing Il6ra in AP neurons attenuates cancer cachexia and AP network hyperactivity, and prolongs lifespan." (PMID 38824130, 2024). "Interleukin-6 (IL-6) is a pivotal immunomodulatory cytokine that plays a crucial role in the pathogenesis of various diseases, including autoimmune disorders, chronic inflammatory conditions, and cancer." (PMID 38576490, 2024). "Likewise, interleukin 6 (IL-6) also involved in the regulation of various pathological condition including cancer." (PMID 38957610, 2024). "Notably, integrating anti-IL-6 therapies with ICB represents a promising approach to overcoming immunosuppression driven by cancer-promoting inflammation." (PMID 39034318, 2024). "CAFs induce EMT by secreting IL-6 and promoting cancer cell migration." (PMID 38244071, 2024). "Also, the mentioned connection between IL-6 and apoptosis has been shown in certain cancer cell lines, where IL-6 increases caspase-3 activation, thus further activating the progression of programmed cell death." (PMID 39456869, 2024). "Similarly, inhibitors targeting the IL-6 pathway, like tocilizumab, have entered clinical trials to evaluate their potential in mitigating cancer-related inflammation and cachexia, showcasing the therapeutic versatility of targeting cytokine pathways." (PMID 39034318, 2024). "Moreover, interleukin-6 (IL-6) overproduction in the niche has been reported to boost the number of CSCs by directing surrounding stem cells towards a cancer phenotype in As-induced malignant epithelial cells." (PMID 38519574, 2024). "Next, to investigate whether IL6-dependent STAT3 activation is essential for CALB2 expression in cancer cells, various concentrations of stattic (MCE, #HY-13818), a potent STAT3 inhibitor, were added to the cancer cells with rhIL6 treatment." (PMID 39358777, 2024). "IL-6 from CAFs induces EMT through STAT3 in various cancers." (PMID 39201656, 2024). "Similarly, high expression of stromal IL6 at the mRNA level acted as a marker of poorer cancer-specific survival in CRC." (PMID 39766336, 2024). "Some of the suggested mechanisms for physical activity protective effect against cancer are regulation of interleukin-6 (IL-6) activity, reduction in insulin growth factor-1 (IGF-1) levels, mitochondrial function enhancement in apoptosis of cancer cells, and epigenetic alterations." (PMID 38768241, 2024). "Additionally, the cell culture media of transfected and non-transfected MCF-7 cells were analyzed, revealing a significant increase in IL-6 protein secretion when cancer cells were transfected with anti-miR-26a-5p (p < 0.01)." (PMID 38338683, 2024).